KCNQ1 (potassium voltage-gated channel subfamily Q member 1)
Description:
Pore-forming subunit of the voltage-gated potassium (Kv) channel involved in the regulation of cardiomyocyte excitability and important in normal development and functions of myocardium, inner ear, stomach and colon. Associates with KCNE beta subunits that modulates current kinetics. Induces a voltage-dependent current by rapidly activating and slowly deactivating potassium-selective outward current. Also promotes a delayed voltage activated potassium current showing outward rectification characteristic (By similarity). During beta-adrenergic receptor stimulation, participates in cardiac repolarization by associating with KCNE1 to form the I(Ks) cardiac potassium current that increases the amplitude and slows down the activation kinetics of outward potassium current I(Ks) (By similarity). Muscarinic agonist oxotremorine-M strongly suppresses KCNQ1/KCNE1 current. When associated with KCNE3, forms the potassium channel that is important for cyclic AMP-stimulated intestinal secretion of chloride ions. This interaction with KCNE3 is reduced by 17beta-estradiol, resulting in the reduction of currents (By similarity). During conditions of increased substrate load, maintains the driving force for proximal tubular and intestinal sodium ions absorption, gastric acid secretion, and cAMP-induced jejunal chloride ions secretion (By similarity). Allows the provision of potassium ions to the luminal membrane of the secretory canaliculus in the resting state as well as during stimulated acid secretion (By similarity). When associated with KCNE2, forms a heterooligomer complex leading to currents with an apparently instantaneous activation, a rapid deactivation process and a linear current-voltage relationship and decreases the amplitude of the outward current. When associated with KCNE4, inhibits voltage-gated potassium channel activity. When associated with KCNE5, this complex only conducts current upon strong and continued depolarization. Also forms a heterotetramer with KCNQ5; has a voltage-gated potassium channel activity. Binds with phosphatidylinositol 4,5-bisphosphate. KCNQ1-KCNE2 channel associates with Na(+)-coupled myo-inositol symporter in the apical membrane of choroid plexus epithelium and regulates the myo-inositol gradient between blood and cerebrospinal fluid with an impact on neuron excitability (By similarity). [Isoform 2]: Non-functional alone but modulatory when coexpressed with the full-length isoform 1.
Synonyms: KCNA8; KCNA9; KVLQT1; Kv7.1; JLNS1; LQT1; ATFB1; ATFB3; Kv1.9; LQT; RWS; SQT2; WRS
Tractability: Small molecule: an approved drug acts on it; a structure with a bound ligand is known; a high-quality ligand is known; it belongs to a druggable protein family. Antibody: UniProt places it where antibodies can reach, with high confidence; its Gene Ontology location is reachable by antibodies, with high confidence; UniProt predicts a signal peptide or a membrane-spanning region; the Human Protein Atlas places it where antibodies can reach. PROTAC: UniProt records ubiquitination sites on it; ubiquitination databases record sites on it; a small molecule that binds it is known.
Target class: Potassium channels; Ion channel; Voltage-gated ion channel; Voltage-gated potassium channel
Chemical probes: ML277 (high quality)
Safety:
Unwanted effects reported when the protein is acted on. In parentheses: how it was acted on, where the effect was seen, and who reports it.
atrial fibrillation (activation; cardiovascular system; sources: Urban et al. (2012), Bowes et al. (2012))
deafness (inhibition; cardiovascular system; sources: Urban et al. (2012), Bowes et al. (2012))
gastrointestinal symptoms (inhibition; cardiovascular system; sources: Urban et al. (2012), Bowes et al. (2012))
long QT syndrome (inhibition; cardiovascular system; sources: Bowes et al. (2012), Urban et al. (2012))
hearing impairment (inhibition; cardiovascular system; source: Urban et al. (2012))
potential hearing impairment (inhibition; cardiovascular system; source: Bowes et al. (2012))
new-onset diabetes after transplantation (source: ClinPGx)
Gene: Protein-coding gene on chromosome 11 (2,444,654 to 2,849,105, forward strand). Ensembl gene ENSG00000053918.
Subcellular location: Cell membrane; Cytoplasmic vesicle membrane; Early endosome; Membrane raft; Endoplasmic reticulum; Basolateral cell membrane; Apical cell membrane
Subcellular location (Human Protein Atlas): Endoplasmic reticulum; Cytosol; Plasma membrane
Pathways (Reactome):
Muscle contraction: Phase 2 - plateau phase; Phase 3 - rapid repolarisation
Neuronal System: Voltage gated Potassium channels
Gene Ontology:
Molecular function: calmodulin binding; delayed rectifier potassium channel activity; outward rectifier potassium channel activity; phosphatidylinositol-4,5-bisphosphate binding; protein binding; protein kinase A catalytic subunit binding; protein kinase A regulatory subunit binding; protein phosphatase 1 binding; scaffold protein binding; transmembrane transporter binding; ubiquitin protein ligase binding; voltage-gated potassium channel activity; voltage-gated potassium channel activity involved in atrial cardiac muscle cell action potential repolarization; voltage-gated potassium channel activity involved in cardiac muscle cell action potential repolarization; voltage-gated potassium channel activity involved in ventricular cardiac muscle cell action potential repolarization; monoatomic ion channel activity
Biological process: atrial cardiac muscle cell action potential; cardiac muscle contraction; cellular response to cAMP; cellular response to xenobiotic stimulus; membrane repolarization during action potential; membrane repolarization during atrial cardiac muscle cell action potential; membrane repolarization during cardiac muscle cell action potential; membrane repolarization during ventricular cardiac muscle cell action potential; positive regulation of cardiac muscle contraction; positive regulation of heart rate; positive regulation of potassium ion transmembrane transport; potassium ion export across plasma membrane; potassium ion transmembrane transport; regulation of atrial cardiac muscle cell membrane repolarization; regulation of heart rate by cardiac conduction; regulation of membrane potential; regulation of membrane repolarization; regulation of ventricular cardiac muscle cell membrane repolarization; ventricular cardiac muscle cell action potential; action potential; cardiac muscle cell contraction; cellular response to epinephrine stimulus; inner ear development; intestinal absorption; regulation of gastric acid secretion; and 36 more
Cellular component: basolateral plasma membrane; cytoplasm; cytoplasmic vesicle membrane; early endosome; endoplasmic reticulum; late endosome; lysosome; membrane raft; monoatomic ion channel complex; plasma membrane; voltage-gated potassium channel complex; apical plasma membrane; membrane; apical part of cell; basal part of cell; basolateral part of cell; ciliary base; cytoplasmic vesicle; endomembrane system; lumenal side of membrane; neuron projection; neuronal cell body; potassium channel complex; transport vesicle
Genetic constraint (gnomAD): Loss-of-function variants: 50 observed, 69.15 expected, observed/expected ratio (o/e) 0.72, 90% interval 0.57 to 0.92. The synonymous counts are far from expectation, so gnomAD's model fits this gene poorly and the ratio says little. Missense variants: 790 observed, 863.39 expected, observed/expected ratio (o/e) 0.92, 90% interval 0.86 to 0.97. Synonymous variants: 450 observed, 372.79 expected, observed/expected ratio (o/e) 1.21, 90% interval 1.12 to 1.3.
Gene-disease validity (ClinGen):
ClinGen rates the evidence that KCNQ1 causes each of these diseases.
Jervell and Lange-Nielsen syndrome (autosomal recessive): Definitive. An autosomal recessive inherited syndrome caused by mutations in the KCNE1 and KCNQ1 genes.
long QT syndrome (autosomal dominant): Definitive.
short QT syndrome (autosomal dominant): Strong.
hypertrophic cardiomyopathy (autosomal dominant): Disputed. A condition in which the myocardium is hypertrophied without an obvious cause.
Homologues: Orthologues: chimpanzee KCNQ1 (99% identical), macaque KCNQ1 (98% identical), guinea pig KCNQ1 (91% identical), pig KCNQ1 (89% identical), rat Kcnq1 (89% identical), mouse Kcnq1 (88% identical), dog KCNQ1 (84% identical), rabbit KCNQ1 (70% identical), tropical clawed frog kcnq1 (70% identical). Paralogues in human: KCNQ5 (38% identical), KCNQ2 (37% identical), KCNQ4 (36% identical), KCNQ3 (35% identical), KCNB2 (15% identical), KCNC4 (14% identical), KCNC2 (14% identical), KCNC1 (14% identical), KCNC3 (14% identical), KCND1 (14% identical), KCND3 (14% identical), and 19 more.
Diseases named in the same sentence as KCNQ1 in open-access papers:
KCNQ1 is named in the same sentence as 241 diseases in open-access papers, as found by Europe PMC text mining. Sharing a sentence is not in itself a finding about the gene and the disease. The quoted sentences say what the papers report.
long QT syndrome (167 papers, 2008 to 2026). "A secondary finding included a heterozygous, paternally inherited pathogenic variant in KCNQ1 (NM_000218.2; c.905C>T, p.A302V), associated with long QT syndrome (MIM: 192500)." (PMID 41531943, 2026). "We also considered the potential contribution of the pathogenic KCNQ1 variant, associated with long QT syndrome and sudden cardiac death." (PMID 41531943, 2026). "In this sense, the KCNQ1 gene that codes for the potassium channel protein is associated with epilepsy and long QT syndrome." (PMID 41062843, 2026). "Over 1000 KCNQ1 missense variants, many of which are associated with long QT syndrome, are reported in ClinVar and other databases." (PMID 40724807, 2025). "KCNQ1 is one of the most prominent causes of long QT syndrome, leading to an increased risk of sudden and fatal cardiac arrest among young individuals." (PMID 41561974, 2025). "In this unique case, we have documented the transmission of congenital Long QT Syndrome due to a pathogenic variant in KCNQ1, from a pediatric heart donor to recipient." (PMID 40176271, 2025). "Mutations in the KCNQ1 gene are associated with several heart diseases, including long QT syndrome, short QT syndrome, atrial fibrillation, and sudden cardiac death." (PMID 40724807, 2025). "AC9 weakly labeled KCNQ1 (SS = 0.5 for Veh and NE conditions), which encodes the delayed rectifier potassium IKs channel that is associated with long QT syndrome and requires AC9 for β-AR stimulation." (PMID 40749829, 2025). "One individual was heterozygous for the MYBPC3 p.Gly531Arg pathogenic variant associated with hypertrophic cardiomyopathy (HCM), and two individuals were heterozygous for the KCNQ1 p.Arg397Trp (LP) variant implicated in long QT syndrome (LQTS)." (PMID 40970488, 2025). "Of particular interest were variants unique to specific subpopulations, such as the KCNQ1 variant, rs120074186, which was exclusively present in the Arab subpopulation and linked to Long QT Syndrome." (PMID 38398418, 2024). "Variants on KCNQ1 were also revealed to play a role in the abnormal KCNQ1 trafficking, leading to HF and long QT syndrome." (PMID 38420267, 2024). "We identified the KCNQ1/p.D446E variant in 2/63 patients with long QT syndrome, 30-fold more frequent than in public databases." (PMID 38256028, 2024). "A comprehensive arrhythmia panel identified a pathogenic mutation in KCNQ1, consistent with long QT syndrome (LQTS) type 1." (PMID 38808169, 2024). "KCNQ1 is implicated in long QT syndrome (LQTS) and cardiac arrhythmia; the clinical significance and biological role of KCNQ1 in LUAD is also described." (PMID 38911514, 2024). "In the two probands (from family 2 and 8) with KCNQ1 variants (associated with long QT syndrome), medical treatment with betablockers was prescribed by the treating cardiologist as well as annual follow up in a specialized cardiology clinic." (PMID 38740897, 2024). "For example, variants in KCNQ1 (potassium voltage-gated channel subfamily Q member 1) are one of the most common causes of long QT syndrome in humans, and a KCNQ1 variant is associated with this syndrome in dogs." (PMID 37239348, 2023). "Long QT syndrome (LQTS) stems from pathogenic variants in KCNQ1 (LQT1), KCNH2 (LQT2), or SCN5A (LQT3) and is characterized by action potential duration (APD) prolongation." (PMID 37124559, 2023). "In another patient with Long-QT syndrome, we detected a pathogenic loss-of-function variant in KCNQ1 (p.Gln530Ter)." (PMID 36411388, 2023). "Drug screening based on cardiomyocytes derived from FAHXMUi001-A successfully identified verapamil and lidocaine as alternative therapeutic agents for the treatment of a rare KCNQ1/TRPM4 dual mutation long QT syndrome patient." (PMID 36010573, 2022).
long QT syndrome (continued). "We identified an association of rare variants in aggregate at Mendelian long-QT syndrome (LQTS) genes (KCNQ1 [QT and JT], KCNH2 [QT])." (PMID 36050321, 2022). "In this study we detected one medically actionable variant in KCNQ1, which is associated with long QT syndrome and has immediate implications for patient management." (PMID 34148116, 2022). "Similar observations have been made for KCNQ1-related long-QT syndrome, which has already been shown to be associated with insulin-mediated hypoglycemia." (PMID 35897673, 2022). "KCNQ1 loss-of-function mutations prolong cardiac action potential duration and are associated with long QT syndrome, which predispose patients to lethal ventricular arrhythmia." (PMID 35957984, 2022). "Molecular autopsy revealed an intronic variant in the KCNQ1 gene (c.683 + 5G > A), classified as likely pathogenic for long QT syndrome according to the guidelines provided by the American College of Medical Genetics and Genomics." (PMID 36232963, 2022). "Reduction in current densities due to loss-of-function KCNQ1 mutations or a reduction in repolarization reserve during β-adrenergic stimulation is thought to underlie long QT syndrome phenotypes with increasing susceptibility to arrhythmia." (PMID 36076956, 2022). "The long QT patient-specific iPSC line carrying KCNQ1/TRPM4 dual mutations also represents a tool for further understanding long QT syndrome pathogenesis." (PMID 36010573, 2022). "Autosomal dominant loss-of-function mutations in KCNQ1 result in long QT syndrome, called Romano–Ward Syndrome (RWS), while autosomal recessive mutations lead to Jervell and Lange-Nielsen syndrome (JLNS), associated with deafness." (PMID 33498651, 2021). "Missense substitution Thr96Arg in KCNQ1 (dbSNP: rs1337409061) was recently submitted to ClinVar as likely pathogenic and associated with long QT syndrome (ClinVar id: VCV000983021.1)." (PMID 34691145, 2021). "The variant c.926C > T (p.T309I) in KCNQ1 gene was identified in 10 putatively unrelated Czech families with long QT syndrome (LQTS)." (PMID 33574382, 2021). "The current study has examined the most common long QT syndrome-susceptibility genes encoding key ion channel subunits KCNQ1 (LQT1) and KCNH2 (LQT2)." (PMID 35237176, 2021). "Loss-of-function mutations in KCNQ1 causes long QT syndrome along with glucose-stimulated hyperinsulinemia, increased C-peptide and postprandial hypoglycemia." (PMID 32164657, 2020). "We observed variants at loci containing genes previously established to cause monogenic long-QT syndrome and encoding ion channels or channel-interacting proteins (KCNQ1, KCNH2, SCN5A-SCN10A, and KCNE1)." (PMID 32527199, 2020). "Mutations in cardiac KCNQ1/KCNE1 channels are the most common cause of congenital defects that cause long QT syndrome (LQTS)." (PMID 33322401, 2020). "In this report, a case of long QT syndrome with KCNQ1 gene mutation induced TWA in the head-up tilt test (HUTT), which has not been reported yet." (PMID 32443288, 2020). "In this report, a case of long QT syndrome (LQTS) with KCNQ1 gene mutation induced TWA in the head-up tilt test (HUTT), which has not been reported yet." (PMID 32443288, 2020). "KCNQ1 harbors more than 300 loss-of-function mutations that reduce IKs currents and are associated with long QT syndrome (LQTS)." (PMID 32678288, 2020). "In rare cases, LOM of IC2 has been reported in families with KCNQ1 germline variants which additionally cause long-QT syndrome (LQTS)." (PMID 32393365, 2020).